CHI3L1 (chitinase 3 like 1)
Diseases named in the same sentence as CHI3L1 in open-access papers (continued):
Sharing a sentence is not in itself a finding about the gene and the disease.
cancer (continued). "CHI3L1 overexpression increased the expression of LC3-II and LC3 puncta formation in Hep3B and SW480 cancer cell lines." (PMID 37340009, 2023). "Under ER stress conditions induced by the application of thapsigargin, the depletion of CHI3L1 induces ER stress through the upregulation of PERK and PERK downstream factors (eIF2α and ATF4) in both normal and cancer cells." (PMID 37215572, 2023). "CHI3L1 regulates the reprogramming of macrophages, development of CD4+ T cells, and cytotoxic activity of CD8+ T cells during cancer progression." (PMID 37958973, 2023). "Double depletion of CHI3L1 and SOD1 reduced the PERK protein levels compared with the depletion of CHI3L1 cancer cells." (PMID 37215572, 2023). "Based on our results, depletion of CHI3L1 in cancer cells activates UPR and induces stress response, providing a new strategy for anti-cancer therapy." (PMID 37215572, 2023). "The secreted CHI3L1 activated AKT, ß-catenin and NF-κB signal pathways in cancer cells and macrophages to foster a protumor TME characterized by activating M2 macrophages and increasing the population of regulatory T cells." (PMID 34987649, 2022). "These are worthwhile to point out that CST1, CHI3L1, UBD, and INHBA genes were verified by the GEPIA in both COAD and READ cancer types while ASCL2 was verified only in COAD cancer type by the GEPIA." (PMID 35333898, 2022). "The human CLPs include YKL-40, YKL-39, and SI-CLP, of which YKL-40 (CHI3L1) is the best-studied and is upregulated in a variety of inflammatory and neurodegenerative diseases and cancers." (PMID 36372883, 2022). "Several proteins involved in carcinogenesis or leukemogenesis are increased for clinical responders (ANO6, CHI3L1, CTSG, ELANE and FGR), suggesting that the sensitivity to ATRA/VP additionally depends on more general functions involved in cancer development." (PMID 33946813, 2021). "The target of miR-24 is the chitinase 3-like 1 (CHI3L1) gene, which is related to the synthesis of a secretory glycoprotein involved in different cancers and inflammatory conditions." (PMID 35011442, 2021). "YKL-40, also known as chitinase-3-like 1 (CHI3L1), is a glycoprotein that is expressed and secreted by various cell types, including cancers and macrophages." (PMID 32883029, 2020). "Subsequently, p-STAT3 can induce the downstream target genes, such as CCL2, CCL5, ICAM-1, SNAI1, chitinase-3-like 1 (CHI3L1), FBJ murine osteosarcoma viral oncogene homolog (FOS), and Skp2, that promote various cellular processes for cancer progression." (PMID 28157698, 2017). "At the same time, CHI3L1-induced upregulation of MMP genes in MKN-45 and MDA-MB-231 cancer cells was eliminated when treated with inhibitors." (PMID 28143526, 2017). "Therefore, CHI3L1 could promote the regional or distal metastasis of cancer." (PMID 28143526, 2017). "Influence of chitinase 3-like 1 (CHI3L1) haplotypes and clinicopathologic parameters on cancer recurrence event and survival event of the patients with uterine cervical cancer." (PMID 25203433, 2014). "Influence of chitinase 3-like 1 (CHI3L1) haplotypes and clinicopathologic parameters on cancer recurrence probability and overall survival of the patients with uterine cervical cancer." (PMID 25203433, 2014). "YKL-40 (chitinase 3-like 1, CHI3L1) is a highly conserved glycoprotein produced by cancer cells (including PC), macrophages, neutrophils, and by fetal and embryonic stem cells." (PMID 23840582, 2013). "Taken together, although CHI3L1 is virtually absent in healthy individuals, it is markedly upregulated in various cancer types, where it plays a multifaced role." (PMID 40643503, 2025). "CHI3L1 (chitinase-3-like protein 1, also known as YKL-40) is a non-enzymatic chitinase-like protein produced by various cell types, including macrophages, neutrophils, fibroblasts, endothelial cells, and cancer cells." (PMID 41154593, 2025).
cancer (continued). "CHI3L1 inhibits NK cell cytotoxicity and ADCC by disrupting the cytotoxic machinery, preventing lytic granule polarization to the immune synapse, and hindering downstream JNK signaling, a crucial process for cancer cell apoptosis." (PMID 38533507, 2024). "The role of CHI3L1 in the extracellular matrix (ECM) is currently known to be related to the inhibition of metalloproteinases (MMPs) by this protein and influences the motility and invasiveness of cancer cells." (PMID 39399677, 2024). "We identified several potential CHI3L1 target proteins, including VEGFA, TGF-β1, Cluster of Differentiation 74 (CD74), IL-6, inhibitor of DNA binding 3 (ID3), MMP9, CXCL8, and SPP1, in this type of cancer." (PMID 38177294, 2024). "Among chitinases, CHI3L1 is the most extensively studied in relation to cancer; however, its role in disease has not been fully elucidated, primarily owing to its unique crystalline structure." (PMID 39068486, 2024). "However, it was found that the depletion of CHI3L1 increased CHOP and cleaved caspase-12 levels in cancer cells." (PMID 37215572, 2023). "Our results showed that the depletion of CHI3L1 increased SOD1 expression in cancer cells but not in normal cells." (PMID 37215572, 2023). "In this study we show that exogenous addition of recombinant CHI3L1 protein promoted the AKT and β-catenin pathways in cancer cells, suggesting that stromal-derived CHI3L1 may affect cancer cells in a paracrine manner within the TME." (PMID 34987649, 2022). "Thus, our data indicated that K284 blocks the formation of the CHI3L1/IL‐13Rα2 complex and the downstream signaling of JNK, AKT, and AP‐1 pathways leading to the inhibition of cancer cell growth." (PMID 34758182, 2022). "RT-qPCR showed the expression of CHI3L1, IL-10, RETNLB (Fizz1), and Arg1, to confirm the M2 macrophages The results showed that the expression level of both CD68 and CD206 were significantly increased in cancer tissues compared with paracancerous tissues." (PMID 35637970, 2022). "YKL-40 (also known as chitinase-3-like 1 [CHI3L1]) is a conserved, secreted chitinase-like protein (CLP) found in elevated levels in many different diseases characterized by inflammation and extracellular remodeling, including cancer." (PMID 35631632, 2022). "Moreover, in cells with CHI3L1 deletion, the suppression effects of K284 on the AKT signaling, cancer cell growth and migration, and apoptotic cell death were abolished." (PMID 36615523, 2022). "Additionally, CHI3L1 plays a significant role in CD4+ T cell development and T helper 2 (Th2)-mediated inflammation, while CHI3L1 decreases responses of Th1 and cytotoxic CD8+ T cells during cancer progression." (PMID 34987649, 2022). "We suggest that Chi3l1 negatively regulates Th1 and CTL functions and dNP2-siChi3l1 complex could be an alternative cancer immunotherapy approach for lung metastasis to enhance Th1 and CTL functions but decrease of Th2." (PMID 29403003, 2018). "The mice injected with the CHI3L1 protein exhibited much higher lung metastasis luciferase signals than the control (i.e., mice injected with only PBS), indicating that CHI3L1 protein promoted cancer metastasis in vivo." (PMID 28143526, 2017). "Additionally, CHI3L1, also known as YKL-40, is a secreted 40 kDa glycoprotein that is upregulated in several human cancers and other diseases characterized by chronic inflammation." (PMID 27801851, 2016). "Chitinase 3-like 1 (CHI3L1) is located on chromosome 1q32.1, and the product, YKL-40, a 40-kDa glycoprotein, is secreted by numerous human cells such as cartilage, synovium, endothelial cells, inflammatory cells, and cancer cells." (PMID 26452028, 2015). "No CHI3L1 mRNA expression was found in the cancer cells, in macrophages infiltrating the solid tumor areas, or in non-malignant tissue." (PMID 26425658, 2015). "Furthermore, functions of CHI3L1 and S100A9 in cancer cells are also inversely correlated each other." (PMID 26431492, 2015).
cancer (continued). "YKL40 (CHI3L1) is a member of the “mammalian chitinase–like proteins,” secreted by activated macrophages and neutrophils during inflammation in various tissues including liver, smooth muscle and cancer cells." (PMID 23226395, 2012). "CHI3L1 (YKL-40) is up-regulated in a variety of inflammatory conditions and cancers." (PMID 20540736, 2010). "However, the depletion of CHI3L1 induces ER stress and eventually activates the unfolded protein response, especially the activation of Protein kinase R-like endoplasmic reticulum kinase (PERK), which regulates protein synthesis in cancer cells." (PMID 37215572, 2023). "CHI3L1 may not affect ER stress owing to the lack of misfolded proteins in normal cells, but instead activate ER stress as a defense mechanism only in cancer cells." (PMID 37215572, 2023). "Moreover, the relationship between tumoral Rab37 expression and circulation CHI3L1 level has never been examined in human cancer patients." (PMID 34987649, 2022). "However, the effect of M2 macrophage-derived CHI3L1 on cancer metastasis is not previously addressed." (PMID 28143526, 2017). "Currently, no cancer therapeutic agent related to CHI3L1 or YKL 40 has been reported." (PMID 26452028, 2015). "Analyzing the relationship among CHI3L1 SNPs or haplotypes, clinicopathologic variables, cancer recurrence, and patient survival, we could not demonstrate any significant association between CHI3L1 SNPs and these characteristics." (PMID 25203433, 2014). "YKL-40, also known as chitinase-3-like 1 (CHI3L1) or human cartilage glycoprotein-39, is a 40 kDa secreted glycoprotein with two potential N-linked glycosylation sites which has been proposed as a biomarker in a variety of cancers but has not received FDA approval." (PMID 26509158, 2015). "We confirmed that the depletion of CHI3L1 induced the phosphorylation of PERK and increased the eIF2α and ATF4 levels in cancer cells, but not normal cells." (PMID 37215572, 2023). "Unlike PRUNE2 and CHI3L1 proteins, KLRC3 gene coding for NKG2E protein, has never been reported in cancer." (PMID 27641066, 2017). "CHI3L1(YKL40) may play an important role in the complex processes involved in cancer progression; therefore, while modulating CHI3L1(YKL40) may not be sufficient to comprehensively treat all cancers, it shows promise against some cancers." (PMID 38543093, 2024).
cardiovascular disease (55 papers, 2009 to 2025). "Only a single association study of polymorphisms of the CHI3L1 locus and cardiovascular disease have been conducted." (PMID 22937056, 2012). "Polymorphisms of CHI3L1 are associated with inter-individual YKL-40 levels and YKL-40 is associated with an increased mortality and is elevated in patients with cardiovascular disease." (PMID 22937056, 2012). "A recent review demonstrated CHI3L1 could potentially be a predictor of cardiovascular disease, as it has been shown to be associated with vascular inflammation, and elevated levels are associated with cardiovascular disease progression." (PMID 40278353, 2025). "In contrast, according to our findings, we speculated that CHI3L1 as a prognostic factor for cardiovascular diseases may be associated with its role in promoting angiogenesis and forming unstable atherosclerotic plaques." (PMID 34349665, 2021). "Chitinase-3-like protein 1 (CHI3L1, also known as YKL-40) and chitotriosidase (CHIT1) are proteins expressed in response to inflammation and have both been associated with cardiovascular disorders." (PMID 30311184, 2018). "No other direct antagonistic targeting agent for CHI3L1 exists at this time, but future availability of such reagents will enable deeper investigation as to the role, function and therapeutic potential of targeting CHI3L1 in cardiovascular disease." (PMID 25358394, 2014). "More recently, the plasma of patients with cardiovascular disease was shown to contain a novel biomarker—chitinase‐3‐like‐1 (CHI3L1, in mice), also known as YKL‐40 or BRP‐3912, 13, 14, 15, 16, 17, 18, 19, 20, 21, 22 in humans." (PMID 40013912, 2025). "YKL-40 (CHI3L1), an emerging biomarker in cardiovascular disease, is named for its first 3 terminal amino acids [tyrosine (Y), lysine (K), and leucine (L)] and its apparent molecular weight." (PMID 30111325, 2018). "YKL-40 (CHI3L1) is a novel biomarker for inflammation, tissue remodeling, and fibrosis, as well as cardiovascular diseases." (PMID 30111325, 2018). "Rathcke at al. examined CHI3L1 levels in patients with CHF and in age-matched controls without cardiovascular disease." (PMID 31936828, 2020).
infection (54 papers, 2012 to 2026). The state of being infected such as from the introduction of a foreign agent such as serum, vaccine, antigenic substance or organism. "They demonstrate that CHI3L1 stimulates the infection caused by these VOC by stimulating the expression and accumulation of ACE2 and SPP." (PMID 35735790, 2022). "Additional studies of the importance of CHI3L1 and its roles in infections caused by SC2 variants are warranted." (PMID 35735790, 2022). "NF-κB target genes (i.e., C3, Chi3l1, Fas, Gadd45β, Hmox1, Ptx3, Saa3, Tlr2) were also abundant in DEGs in which upregulation during infection was impaired by CCR5-deficiency." (PMID 31506064, 2019). "We showed that within infected children, CHI3L1 levels were higher in haematuria positive compared to haematuria negative individuals, suggesting that elevated CHI3L1 levels are associated with infection and morbidity in S. haematobium infection." (PMID 23145202, 2012). "Because studies from our laboratory have demonstrated that chitinase 3-like-1 (CHI3L1) stimulates ACE2 and Spike (S) priming proteases that mediate SC2 infection, studies were undertaken to determine if interventions that target CHI3L1 are effective inhibitors of SC2 viral variant infection." (PMID 35735790, 2022). "Similarly, Chi3l1 (encoding the prototypical chitinase-like protein) is also upregulated in second infection and can attenuate inflammasome activation to minimise collateral tissue damage." (PMID 33752799, 2021). "In addition, NF-κB target genes (i.e., C3, Chi3l1, Fas, Gadd45β, Hmox1, Ptx3, Saa3, Tlr2) were abundant in the DEGs in which upregulation during infection was impaired by CCR5-deficiency." (PMID 31506064, 2019). "Infection and inflammation stimulate the production of CHI3L1, which plays a major role in tissue injury, inflammation, tissue repair, and remodeling responses." (PMID 38962736, 2024). "Violin plots show that Kp52145 infection increased the levels of the M(Kp) markers arg1, il10, chi3l1, ido, pparγ, mrc1, nos2, isg56 and il1rn (Fig EV5A–E)." (PMID 36337046, 2022). "In keeping with the importance of ACE2 and SPP in SC2 infection and the impressive ability of CHI3L1 to stimulate these moieties, these studies focused on the relationships between CHI3L1 and ACE2 in infections caused by the α, β γ, δ, and ο variants." (PMID 35735790, 2022). "In keeping with this presumption, we believe that CHI3L1 will also regulate VOI infection, replication, and symptom generation by altering ACE2 and SPP." (PMID 35735790, 2022). "In our study, we found significantly increased expression of CHI3L1 during sub-clinical (FC-4.05) and clinical infection (FC-9.99) which depicts the activation of host resistance and host tolerance for infection." (PMID 32518370, 2020). "The concentration of CHI3L1 was determined together with key infection or inflammation parameters at the local level (bacterial load, neutrophil influx, interleukin (IL)-8 and IL1beta, IL-6, RANTES/CCL5 levels)." (PMID 29892291, 2018). "Compared to expression levels in uninfected quarters, E. coli 1303 infection significantly induced IL-1beta, IL-6, and IL-8 concomitantly with CHI3L1 in these infected quarters." (PMID 29892291, 2018). "Frozen plasma from 410 children presenting to the Jinja Regional Hospital in Uganda with suspected infection was used to measure biomarkers of endothelial (Angiopoietin-2, sFlt-1, sVCAM-1, sICAM-1) and immune (IL-6, IP-10, sTNFR-1, CHI3L1) activation." (PMID 28419100, 2017). "When combining mammary inoculation of LPS or LTA prior to a local S. aureus infection, we were able to modulate the innate immune response, reduce local bacterial loads, and induce either LCN2 or CHI3L1 at 24 h post-infection." (PMID 28791009, 2017). "This study was designed to investigate this novel aspect in the pathogenesis of infection in burns, and the effect of modulating CHI3L1 expression in the context of severe burn injury in a mouse model." (PMID 26528713, 2015).